EXOSC8 (exosome component 8)
Description:
Non-catalytic component of the RNA exosome complex which has 3'->5' exoribonuclease activity and participates in a multitude of cellular RNA processing and degradation events. In the nucleus, the RNA exosome complex is involved in proper maturation of stable RNA species such as rRNA, snRNA and snoRNA, in the elimination of RNA processing by-products and non-coding 'pervasive' transcripts, such as antisense RNA species and promoter-upstream transcripts (PROMPTs), and of mRNAs with processing defects, thereby limiting or excluding their export to the cytoplasm. The RNA exosome may be involved in Ig class switch recombination (CSR) and/or Ig variable region somatic hypermutation (SHM) by targeting AICDA deamination activity to transcribed dsDNA substrates. In the cytoplasm, the RNA exosome complex is involved in general mRNA turnover and specifically degrades inherently unstable mRNAs containing AU-rich elements (AREs) within their 3' untranslated regions, and in RNA surveillance pathways, preventing translation of aberrant mRNAs. It seems to be involved in degradation of histone mRNA. The catalytic inactive RNA exosome core complex of 9 subunits (Exo-9) is proposed to play a pivotal role in the binding and presentation of RNA for ribonucleolysis, and to serve as a scaffold for the association with catalytic subunits and accessory proteins or complexes. EXOSC8 binds to ARE-containing RNAs.
Synonyms: OIP2; RRP43; bA421P11.3; Rrp43p; EAP2; p9; CIP3; PCH1C
Tractability: Small molecule: a structure with a bound ligand is known. PROTAC: ubiquitination databases record sites on it; its protein half-life has been measured.
Gene: Protein-coding gene on chromosome 13 (36,998,816 to 37,025,881, forward strand). Ensembl gene ENSG00000120699.
Subcellular location: Cytoplasm; Nucleus; Nucleus, nucleolus
Subcellular location (Human Protein Atlas): Mitotic chromosome; Nucleoli fibrillar center; Cytosol; Nucleoplasm; Vesicles
Pathways (Reactome):
Metabolism of RNA: Butyrate Response Factor 1 (BRF1) binds and destabilizes mRNA; KSRP (KHSRP) binds and destabilizes mRNA; Major pathway of rRNA processing in the nucleolus and cytosol; Nuclear RNA decay; Tristetraprolin (TTP, ZFP36) binds and destabilizes mRNA; mRNA decay by 3' to 5' exoribonuclease
Cellular responses to stimuli: ATF4 activates genes in response to endoplasmic reticulum stress
Gene Ontology:
Molecular function: identical protein binding; mRNA 3'-UTR AU-rich region binding; protein binding; RNA exonuclease activity
Biological process: RNA catabolic process; RNA processing; exonucleolytic trimming to generate mature 3'-end of 5.8S rRNA from tricistronic rRNA transcript (SSU-rRNA, 5.8S rRNA, LSU-rRNA); nuclear mRNA surveillance; nuclear polyadenylation-dependent rRNA catabolic process; rRNA catabolic process; TRAMP-dependent tRNA surveillance pathway; U1 snRNA 3'-end processing; U4 snRNA 3'-end processing; U5 snRNA 3'-end processing
Cellular component: cytoplasm; cytosol; exosome (RNase complex); fibrillar center; nucleolus; nucleoplasm; nucleus; cytoplasmic exosome (RNase complex); nuclear exosome (RNase complex); nucleolar exosome (RNase complex); exoribonuclease complex
Genetic constraint (gnomAD): Loss-of-function variants: 15 observed, 9.31 expected, observed/expected ratio (o/e) 1.61, 90% interval 1.04 to 1.94. That is too few expected variants to judge how well the gene tolerates losing a copy. Missense variants: 111 observed, 118.52 expected, observed/expected ratio (o/e) 0.94, 90% interval 0.8 to 1.1. Synonymous variants: 39 observed, 40.46 expected, observed/expected ratio (o/e) 0.96, 90% interval 0.75 to 1.26.
Homologues: Orthologues: chimpanzee EXOSC8 (99% identical), rabbit EXOSC8 (98% identical), macaque EXOSC8 (97% identical), dog EXOSC8 (96% identical), guinea pig EXOSC8 (95% identical), pig EXOSC8 (94% identical), rat Exosc8 (92% identical), mouse Exosc8 (91% identical), tropical clawed frog exosc8 (75% identical), zebrafish exosc8 (71% identical), Caenorhabditis elegans exos-8 (24% identical). Paralogues in human: EXOSC7 (28% identical), EXOSC9 (28% identical).
Diseases named in the same sentence as EXOSC8 in open-access papers:
EXOSC8 is named in the same sentence as 51 diseases in open-access papers, as found by Europe PMC text mining. Sharing a sentence is not in itself a finding about the gene and the disease. The quoted sentences say what the papers report.
pontocerebellar hypoplasia (6 papers, 2018 to 2021). Pontocerebellar hypoplasias (PCH) are a rare heterogeneous group of diseases characterized by hypoplasia and atrophy and/or early neurodegeneration of the cerebellum and pons. "Recently, pathogenic variants in genes encoding both structural and catalytic subunits of the RNA exosome have been linked to human disease, such as EXOSC3 and EXOSC8 related forms of pontocerebellar hypoplasia, representing recessive neurodegenerative diseases." (PMID 34944310, 2021). "Recessive variants in exosome components EXOSC3, EXOSC8, and RBM7 cause various constellations of pontocerebellar hypoplasia (PCH), spinal muscular atrophy (SMA), and central nervous system demyelination." (PMID 29727687, 2018). "Recessive variants in exosome components EXOSC3, EXOSC8, and RBM7 cause various constellations of pontocerebellar hypoplasia (PCH), spinal muscular atrophy (SMA), and central nervous system hypomyelination." (PMID 34573300, 2021). "Mutations in EXOSC3, EXOSC8, and EXOSC9 cause several forms of autosomal-recessive neurodegenerative disease, pontocerebellar hypoplasia (PCH), namely, PCH type 1b (PCH1b), PCH1c, and PCH1d, respectively." (PMID 34948199, 2021).
pontocerebellar hypoplasia type 1 (6 papers, 2018 to 2025). "Although the molecular mechanisms for this remain unclear, mutations in the RNA exosome gene RRP43 (EXOSC8) have been shown to be associated with pontocerebellar hypoplasia type 1c." (PMID 31724941, 2019). "Variants of exosome component 3 (EXOSC3), exosome component 8 (EXOSC8) and exosome component 9 (EXOSC9) have all been associated with pontocerebellar hypoplasia type 1 (PCH1B-D)." (PMID 40428407, 2025). "Biallelic variants in EXOSC3, EXOSC8, EXOSC9, and EXOSC1 have been reported in different subtypes of pontocerebellar hypoplasia type 1 (PCH1), which is usually associated with spinal motor neurons dysfunction." (PMID 38017281, 2024).
spinal muscular atrophy (6 papers, 2014 to 2024). A motor neuron disease that affect the muscles, and characterized by muscle weakness and atrophy resulting from progressive degeneration and irreversible loss of the anterior horn cells in the spinal cord (i.e., lower motor neurons) and the brain stem nuclei. "PCH1c with EXOSC8 mutations is characterized by psychomotor deficits, cerebellar and corpus callosum hypoplasia, hypomyelination, and spinal muscular atrophy (SMA)." (PMID 34948199, 2021). "Mutations in its subunits EXOSC8 and EXOSC3 cause pontocerebellar hypoplasia, spinal muscular atrophy (SMA) and central nervous system demyelination." (PMID 27193168, 2016).
colorectal cancer (4 papers, 2020 to 2023). A primary or metastatic malignant neoplasm that affects the colon or rectum. "The oncogenic roles of Exosome Component 8 (EXOSC8) have been confirmed in colorectal carcinoma and prostate cancer." (PMID 37087456, 2023). "They confirmed that the expression of EXOSC8 in colorectal cancer was higher than that in matched normal tissues in clinical samples, and verified the cancer-promoting effect of the gene in cell and animal experiments." (PMID 33981333, 2021). "Additionally, functional experiments also confirmed the oncogenic roles of EXOSC8 in colorectal carcinoma." (PMID 36293016, 2022).
Cerebellar atrophy (1 paper, 2018). Cerebellar atrophy is defined as a cerebellum with initially normal structures, in a posterior fossa with normal size, which displays enlarged fissures (interfolial spaces) in comparison to the foliae secondary to loss of tissue. "The involvement of spinal motor neurons together with cerebellar atrophy, with or without pontine involvement, is a common feature in affected individuals with variants in different exosomal subunit (EXOSC3, EXOSC8, and EXOSC9) and belongs to the spectrum of PCH1-related disorders." (PMID 29727687, 2018).
Cerebellar hypoplasia (1 paper, 2020). Cerebellar hypoplasia is a descriptive term implying a cerebellum with a reduced volume, but a normal shape and is stable over time. "A recent paper reported that human patients with mutations that decrease EXOSC9 expression show cerebellar hypoplasia similar to that observed with mutations in other RNA exosome components such as EXOSC3 and EXOSC8 genes." (PMID 32518284, 2020).
demyelinating disease (1 paper, 2014). A broad group of disorders that affect the myelin sheaths that cover the neurons. "We suggest that increased mRNA levels of ARE-containing myelin proteins (MBP, MOBP) resulting from EXOSC8 deficiency initiate a cascade of downstream events, and the disturbed balance between ARE and non-ARE myelin components results in demyelinating disease." (PMID 24989451, 2014).
Hernia (1 paper, 2024). "Although there is no clear association yet between EXOSC8 genes and the development of hernias, it could be attributed to the weak abdominal wall due to the severe axial hypotonia." (PMID 38017281, 2024).
Intellectual disability (1 paper, 2024). "Moreover, mutations in EXOSC3 and EXOSC9 are also associated with intellectual disability in humans and mutations in EXOSC8 causes behavioral defects in zebrafish." (PMID 39480871, 2024).
cancer (10 papers, 2016 to 2024). A tumor composed of atypical neoplastic, often pleomorphic cells that invade other tissues. "EXOSC8 and EXOSC9 are associated with many diseases, but their role in cancer has recently been uncovered." (PMID 34795329, 2021). "While we have rigorously validated PRIM1 and EXOSC8 as genetic dependencies in cancer, further work is necessary to explore potential therapeutic modalities for targeting them (Supplementary Discussion)." (PMID 32433464, 2020). "Genes encoding exosome complex components are linked to pathologies including cancer (DIS3), immune disorders (EXOSC9 and EXOSC10) and congenital neurological disorders (EXOSC3 and EXOSC8)." (PMID 27543448, 2016). "The role of RBPs in promoting cancer has been confirmed, and DROSHA, EXOSC8, HNRNPC, MRPS31, RPLP2, and SNRPB have also been reported to be related to the occurrence and development of a variety of tumors." (PMID 33981333, 2021).
infection (7 papers, 2014 to 2025). The state of being infected such as from the introduction of a foreign agent such as serum, vaccine, antigenic substance or organism. "At 72 hr post-infection, 49.5% of Exosc8-knockdown Ter119- cells were in G1, in comparison with 36% of control cells (p=1.6 × 10–6)." (PMID 27543448, 2016). "At 24 hr post-infection of fetal liver erythroid precursor cells with shRNA-expressing retrovirus, Exosc8 mRNA declined by 70% (p=0.005)." (PMID 27543448, 2016). "Exosc8 downregulation, without ectopic Kit expression, increased the percentage of R3 cells ~two fold (p=0.003) 48 hr post-infection." (PMID 27543448, 2016).
neurodegenerative disease (3 papers, 2014 to 2021). A disorder of the central nervous system characterized by gradual and progressive loss of neural tissue and neurologic function. "We discovered pathogenic mutations in the exosomal protein gene EXOSC8 in 22 patients with profound infantile neurodegenerative disease combining features of cerebellar and corpus callosum hypoplasia, hypomyelination and SMA." (PMID 24989451, 2014). "Here the authors report that homozygous missense mutations in the exosome subunit, EXOSC8, may cause neurodegenerative disease in infants through the dysregulation of myelin expression." (PMID 24989451, 2014).
neurological disease (3 papers, 2014 to 2021). "Here we show that homozygous missense mutations in EXOSC8 cause progressive and lethal neurological disease in 22 infants from three independent pedigrees." (PMID 24989451, 2014). "Four of these genes have already been implicated in a neurological disease (TMEM67, FGFR1, FRAS1 and EXOSC8), but most variants affect genes that have not previously been connected to human disease phenotypes." (PMID 27457812, 2017).
neurodevelopmental disorder (1 paper, 2022). A behavioral and cognitive disorder with onset during the developmental period that involves impaired or aberrant development of intellectual, motor, or social functions. "Five of these genes are already classified as diagnostic grade genes in the IEM panel (COQ4, ELAC2, MRPL44, MSTO1 and SKIV2L) and three others are diagnostic grade genes in different neurology and neurodevelopmental disorder gene panels (EIF2B4, ELP1, EXOSC8)." (PMID 36229886, 2022).
EXOSC8 also shares sentences with these, for which no sentence is quoted: tumor (9 papers); virus infection (5); pontocerebellar hypoplasia, type 1C (4); breast carcinoma (3); Obesity (3); autoimmune disease (2); lung carcinoma (2); metabolic disease (2); Sepsis (2); type 2 diabetes (2); Arthritis (1); autoimmune disorder (1); cerebellar degeneration (1); diabetes mellitus (1); genetic diseases (1); glioblastoma (1); Graves disease (1); HIV-1 infection (1); Hyperglycemia (1); Hypertonia (1); Hypotonia (1); immune disorders (1); Insulin resistance (1); kernicterus (1); liver cancer (1); malaria (1); melanoma (1); metabolic syndrome (1); Neurodevelopmental delay (1); neuromuscular disease (1).
A further 7 diseases each share a sentence with EXOSC8 in 1 paper.